INS (insulin)
Diseases named in the same sentence as INS in open-access papers (continued):
Sharing a sentence is not in itself a finding about the gene and the disease.
Insulin resistance (continued). "The mechanisms by which obesity and insulin resistance promote CRC are not well understood, although insulin is a crucial component in the regulation of energy metabolism." (PMID 22950808, 2012). "Other top predictors included markers of insulin resistance and the IGF pathway (insulin, IGFBP1, uric acid), sex hormones (free estradiol, SHBG), lipid-soluble micronutrients (vitamin D3, lycopene, CoQ10, alpha-tocopherol) and markers of inflammation (CRP)." (PMID 22912885, 2012). "Despite the difference in insulin resistance between MHO and control groups, we confirmed the high insulin sensitivity of this group compared to MAO and LHO obese groups." (PMID 22413940, 2012). "Their serum fasting insulin, fasting glucose, insulin-like growth factor-1, adiponectin, IGFBP-1, triglyceride concentrations, and the homeostasis assessment model for insulin resistance (HOMA-IR) were evaluated." (PMID 23186039, 2012). "Insulin resistance in SHR is partially ascribed to the characteristic sympathetic hyperactivity they present, which promotes reduced activity of the insulin signaling cascade and, consequently, can reduce GLUT4 translocation and/or expression." (PMID 22897936, 2012). "Ceramides are increased in serum, skeletal muscle and liver of obese rodents and humans, correlate negatively with insulin sensitivity and positively with circulating IL6 thereby implicating ceramides in the development of insulin resistance and inflammation." (PMID 22974251, 2012). "In this report, we describe the selectivity and potency of canagliflozin and characterize its effects on UGE, RTG, glycemic control, glucose-stimulated insulin secretion, energy expenditure, and body weight in preclinical models of T2DM and insulin resistance." (PMID 22355316, 2012). "Glucose, insulin and Homeostasis Model Assessment Insulin Resistance (HOMA-IR) are markers of insulin resistance." (PMID 23300589, 2012). "Insulin resistance, insulin sensitivity and pancreatic beta cell function were measured by the Homeostasis Model Assessment (HOMA-IR), the Quantitative Insulin Sensitivity Check Index (QUICKI) and the HOMA-B respectively." (PMID 22691241, 2012). "Thus, insulin modulation of hCAT-1 expression and activity requires functional A2AAR in HUVECs, a mechanism that may be applicable to diseases associated with fetal insulin resistance, such as gestational diabetes." (PMID 22844517, 2012). "The objective of this study was to evaluate the insulin-sensitizing potential of the combined supplementary chromium(III) propionate complex (CrProp) and thiamine in insulin resistance animal model (rats fed a high-fructose diet)." (PMID 23065486, 2012). "We also examined the relationship between insulin, C-peptide, IGFBP-1, and obesity (BMI or waist-hip ratio (WHR), which are factors related to colorectal adenomas, CRC and insulin resistance." (PMID 22950808, 2012). "Trends for higher insulin resistance (HOMA-IR) and lower insulin sensitivity (WBISI) were seen in subjects with lower serum 25(OH)D concentrations but not statistically significant." (PMID 22966228, 2012). "Metabolic syndrome is characterized by insulin resistance, which is closely related to GLUT4 content in insulin-sensitive tissues." (PMID 22897936, 2012). "C‐peptide levels had a high correlation (P<0.001) with other biochemical indices of insulin resistance such as HOMA‐IR (r=0.78), QUICKI (r=−0.78), and serum insulin levels (r=0.77)." (PMID 23316320, 2012). "Previous studies have confirmed that under the presence of insulin resistance, suppression of FFA by insulin is reduced and the increased level of FFA will enhance small dense LDL level whereas the overall level of LDL-C will be less affected." (PMID 22876749, 2012). "There is a report about significant increase in insulin sensitivity (1/HOMA IR) in subjects with the metabolic syndrome and significant decrease in insulin and insulin resistance among men patients with type II diabetes after Ramadan fasting." (PMID 22963582, 2012).
Insulin resistance (continued). "11β-HSD1 knock-out mice have improved insulin sensitivity, where as the transgenic over-expression of 11β-HSD1 in liver or adipose tissue results in the development of insulin resistance." (PMID 23284633, 2012). "Obese patients also have higher levels of circulating free IGF-1 and serum insulin, and a reduction of obesity remains a potential target of decreasing insulin, IGF-1, and insulin resistance." (PMID 23050155, 2012). "Since PPAR-γ is a target for insulin-sensitizing agents, activation of PPAR-γ induced by telmisartan would be expected to improve insulin resistance and hyperglycemia in animals with high-fat diet-induced obesity." (PMID 23554752, 2012). "Moreover, mitochondrial density is reduced in insulin-resistant skeletal muscle from children, offspring of people with type 2 diabetes, suggesting that impaired mitochondrial oxidative capacity can be an inherited defect and an early marker for the development of insulin resistance." (PMID 22360800, 2012). "Homeostatic Model Assessment of β cell function (HOMA-β) and Insulin Resistance (HOMA-IR) and Quantitative Insulin-sensitivity Check Index (QUICKI) were used for measurement of insulin resistance." (PMID 23029165, 2012). "In our study we found a correlation between ADMA and markers of insulin resistance, and the decrease of ADMA concentrations correlated with a decrease of both TG/HDL ratio and direct markers of insulin resistance such as insulin, HbA1c and HOMA-IR." (PMID 22660895, 2012). "Hepatic insulin resistance and impaired skeletal muscle GLUT-4 expression are accounted for the impaired glucose tolerance and reduced insulin sensitivity in estrogen receptor alpha (ERα) knockout mice." (PMID 22463706, 2012). "Typically, insulin resistance is an early feature of the T2DM condition, which is initially compensated in part by increased production of insulin by pancreatic β-cells (hyperinsulinaemia)." (PMID 21716678, 2012). "But Klotho induces IGF-1 and insulin resistance, whereas dwarf mice with reduced IGF-1 and insulin levels have enhanced insulin sensitivity." (PMID 22683661, 2012). "Markers of insulin resistance, serum fasting insulin and C-peptide concentrations were higher, and HDL-cholesterol concentration lower in the insulin-resistant group." (PMID 22471940, 2012). "HOMA-IR, a well-validated measure of IR was calculated to estimate insulin resistance, and frequently sampled intravenous glucose tolerance testing (FSIGTT) was performed to confirm an insulin resistant state." (PMID 22709547, 2012). "While the exact underlying mechanisms for this discrepancy of insulin sensitivity between different models of RAS overactivation are unknown, it is possible that the low insulinemia present in the RenTgMK mice could protect these mice from the development of insulin resistance." (PMID 23308073, 2012). "By following the “Fetal Insulin Hypothesis,” genetically determined alterations within the insulin signaling cascades, which may, for example, result in impaired glucose tolerance and insulin resistance, could be connected to altered fetal development as well as long-term metabolic changes." (PMID 23213562, 2012). "Among patients with high insulin resistance at baseline, treatment with anti-TNF agents for 12 weeks resulted in significant improvement in insulin sensitivity as evidenced by reduction in the HOMA-IR and increase in the QUICKI indices." (PMID 22691241, 2012). "Since NMDA can promote insulin resistance, and NMDA neurotoxicity can be attenuated or prevented by insulin stimulation." (PMID 22329651, 2012). "Moreover, the lack of leptin action causes increased insulin secretion, which is hypothesized to cause insulin resistance in rodents and humans." (PMID 22524730, 2012). "Insulin resistance markers (insulin, HOMA-IR, HOMA-beta) were consistently among the most important predictors of visceral fat and liver fat, although we included only insulin in the final model due to their high correlations." (PMID 22912885, 2012).
Insulin resistance (continued). "To evaluate the molecular events leading to hepatic insulin resistance in the PINX-P1 rats, we assessed the activity status of the insulin signaling steps that are pivotal to the control of hepatic gluconeogenesis." (PMID 22719949, 2012). "The surrogate parameter for insulin resistance HOMA-IR was elevated ∼3-fold (p<0.01) and the surrogate parameter for insulin sensitivity QUICKI was reduced by 30% (p<0.01) in alb-SREBP 1c mice." (PMID 22363740, 2012). "In subjects with insulin resistance, such as patients with polycystic ovary syndrome, A2AAR activation results in increased insulin sensitivity." (PMID 22844517, 2012). "This probably results from radiation induced apoptosis of pancreatic beta cells, and consequently to decreased insulin production, the thereby induced hyperglycemia, elevated FFA levels and hypertriglyceridemia and insulin resistance." (PMID 23251703, 2012). "Increased ROS production is common to different models of cellular insulin resistance, including those induced by TNF-α, insulin and palmitate treatments." (PMID 22586466, 2012). "Homeostatic Measurement Assessment Insulin Resistance (HOMA-IR) is an evaluation of insulin resistance by using glucose level in blood and insulin of patients while fasting to analysis." (PMID 22737168, 2012). "The importance of the IRS2 isoform in insulin mediated GLUT4 redistribution has been demonstrated by the specific knockout in mice, which develop severe insulin resistance." (PMID 27335671, 2012). "Then, although these trends should be confirmed in large studies because of small sample sizes, these findings suggest that other factors associated with high BMI, but not insulin resistance, may also contribute to the pathophysiology of low serum amylase in non-insulin-resistant individuals." (PMID 22748134, 2012). "HF diet induced a significant increase in fasting glucose concentrations, insulin and subsequently HOMAIR compared to vehicle-ST, demonstrating the presence of the insulin resistance state." (PMID 22457831, 2012). "Compared to controls, ob/ob mice demonstrated greater body mass, fasting blood glucose, serum insulin and cholesterol concentrations, and HOMA-IR (Homeostatic model assessment-insulin resistance)." (PMID 22313574, 2012). "Table II shows the results of serum glucose, insulin and visfatin concentrations, as well as the homeostatic model assessment (HOMA) score, which is a measure of insulin resistance." (PMID 23170114, 2012). "Similar to our previous reports of exercise preventing the development of insulin resistance in the OLETF model, here we demonstrate that exercise also can be used as a treatment to improve insulin sensitivity." (PMID 21918718, 2012). "In Meyer's study, individuals with isolated IGT showed impairments in basal insulin secretion and first-phase insulin release, whereas individuals with isolated IGT showed reduced second-phase insulin release and peripheral insulin resistance." (PMID 22233562, 2012). "Insulin resistance was determined by homeostasis model assessment of insulin resistance (HOMA-IR) and by the insulin sensitivity index (Si) derived from Bergman’s minimal model." (PMID 23144966, 2012). "Animal experiments reveal ezetimibe can reduce the fasting insulin and improve the high-lipid induced impaired glucose tolerance (IGT) in diabetic rats with insulin resistance, but the specific mechanism is still unclear." (PMID 23118741, 2012). "Overall, low dose endotoxemia produced systemic insulin resistance following induction of specific adipose inflammatory pathways (cytokines, chemokines and SOCS) that attenuate insulin signaling in vivo." (PMID 22709547, 2012). "Indices of insulin resistance (HOMA-IR, AUC for insulin) and sensitivity (WBISI) were calculated after oral glucose tolerance test." (PMID 22966228, 2012).
Insulin resistance (continued). "Some studies have reported that rosuvastatin and other statins increase markers of insulin resistance, such as homeostasis model assessment of insulin resistance (HOMA-IR) and fasting insulin levels." (PMID 22831708, 2012). "Given that insulin resistance plays a key role in the pathogenesis of NAFLD, many studies have evaluated the use of insulin sensitizers as a possible treatment for this disease." (PMID 22194737, 2012). "Steatosis severity paralleled a progressive increase in insulin levels (p = 0.002), mean HOMA-IR (p = 0.001) and prevalence of insulin resistance (p = 0.009)." (PMID 22359625, 2012). "NO distillate administration reduced fasting blood glucose, HbA1c, insulin resistance, total cholesterol, low density lipoprotein, atherogenic index, triglyceride-HDL ratio, insulin, and leptin levels." (PMID 23251156, 2012). "However, it is not known why all obese subjects are not insulin-resistant and insulin resistance can also be observed in lean subjects, highlighting the fact that the molecular mechanisms underlying insulin resistance are still largely unknown." (PMID 22471940, 2012). "Low-grade inflammation is considered to be an important mechanism in insulin resistance, and the lipid metabolic regulators PPARα, PPARγ, as well as PGC-1α have been shown to play a role in the regulation of insulin sensitivity." (PMID 23251491, 2012). "This metalloprotease, that also catabolizes insulin and IGF-1, can be competitively inhibited by insulin resistance, impairing Aβ degradation, increasing its neurotoxicity and promoting AD." (PMID 22500228, 2012). "TNFα and IL-6 have been shown to inhibit insulin signaling through inhibitory phosphorylation of IRS1; ablation of these cytokines prevents insulin resistance in cells and in vivo." (PMID 24764512, 2012). "Tissue insulin resistance was evident in the A2bAR KO post HFD, noted by alterations in phosphorylation of Akt, an important downstream signaling component of the insulin pathway." (PMID 22848385, 2012). "Insulin sensitivity and glycemia were assessed using an oral glucose tolerance test (OGTT) and the homeostasis model assessment of insulin resistance (HOMA-IR index) evaluation after 21 or 33 months of chronic treatment." (PMID 22479589, 2012). "Adipocyte-specific overexpression of 11β-HSD1 in mice resulted in the development of visceral obesity, dyslipidemia, and insulin resistance, whereas 11β-HSD1 knock-out mice are resistant to diet-induced obesity and have displayed improved insulin sensitivity." (PMID 23284633, 2012). "As insulin resistance is central to NAFLD, agents that improve insulin sensitivity appear promising." (PMID 21918648, 2011). "Moreover, a negative correlation between fasting plasma ghrelin and insulin was observed, suggesting that hyperinsulinaemia associated with insulin resistance may be an important determinant of decreased plasma ghrelin levels in patients with type 2 diabetes." (PMID 21760816, 2011). "Our data demonstrated that berberine significantly decreased FBG, area under thecurve (AUC), fasting serum insulin (FINS), homeostasis model assessment insulin resistance (HOMA-IR) index,TC, and TG, compared with those of control group." (PMID 20953398, 2011). "The strongest correlation of serum adiponectin levels was with the insulin resistance indexes, serum HDL cholesterol, triglyceride and insulin levels." (PMID 21251282, 2011). "We have recently shown that β-cell mass adaptation to insulin resistance failed in the adult POKO mice, an insulin resistant mouse resulting from the deletion of PPARγ2 in an obese ob/ob background." (PMID 22208362, 2011). "ApoC3Tg mice also manifested severe hepatic insulin resistance assessed by a hyperinsulinemic-euglycemic clamp, which could mostly be attributed to increased hepatic diacylglycerol content, protein kinase C-ε activation, and decreased insulin-stimulated Akt2 activity." (PMID 21793029, 2011).
Insulin resistance (continued). "In our study, we found that fetuin-A was positively correlated with fasting serum insulin and HOMA-IR, the indicators of insulin resistance in type 2 diabetes." (PMID 21556362, 2011). "We used fasting blood glucose (FBG), fasting plasma insulin (FPI), oral glucose tolerance test (OGTT), glycated hemoglobin (HbA1c), and insulin resistance (HOMA-IR) to characterize diabetic individuals." (PMID 21864395, 2011). "Untreated db/db were insulin resistant, as shown by HOMA-IR; silibinin decreased fasting glucose and insulin, reversing insulin resistance." (PMID 21756303, 2011). "When the soluble Klotho protein was intraperitoneally administered to wild-type mice, the insulin and IGF-1 sensitivity of the mice was impaired, indicating that increased Klotho protein in the blood induced insulin resistance, as well as IGF-1 resistance." (PMID 21876806, 2011). "Non-human primates develop features characteristic of the metabolic syndrome, including obesity, insulin resistance and T2DM with insulin signaling and insulin secretory molecular defects similar to humans." (PMID 22125617, 2011). "The fasting glucose-to-insulin ratio and homeostasis model assessment (HOMA) of insulin resistance have been proven to be useful estimates of insulin sensitivity, also in critical illness." (PMID 21276273, 2011). "As TNFα treatment may induce insulin resistance by reactivating the expression of preadipocyte genes in vitro this may be the reason why the majority of miRNAs found in our study are oppositely regulated in differentiated, insulin-sensitive adipocytes and insulin resistant ob/ob mice." (PMID 21731698, 2011). "Homeostasis model assessment of insulin resistance (HOMA-IR) was calculated using fasting glucose and insulin level as a marker of IR." (PMID 22408591, 2011). "The persistent activation of these RAAS components contributes to altered insulin/IGF-1 signaling pathways and ROS formation, which induces endothelial dysfunction and insulin resistance." (PMID 21933140, 2011). "The homeostatic model assessment index (HOMA) is an easy way to evaluate insulin resistance; therefore, in this study, the FFAs and HOMA were used to explore the effects of EA on enhancing the hypoglycemic effect of exogenous insulin." (PMID 21754922, 2011). "This is not surprising given the known relation between liver steatosis and the development of insulin resistance; the reduction in steatosis induced by NCX 1000 thus contributing to improve insulin sensitivity." (PMID 22013536, 2011). "Only insulin resistance indices (HOMA-IR and ISI) were indicative of reduced insulin sensitivity, as would be expected in obese subjects." (PMID 21663607, 2011). "This upregulation of insulin signaling proteins was also obtained in a STZ-induced diabetic rat and in a steroid-induced insulin resistance rat model." (PMID 21754922, 2011). "As the elevated insulin levels suggest insulin resistance, an insulin tolerance test was performed to determine the effects of IDFP on insulin resistance." (PMID 22073164, 2011). "The mice that consume the HFD gradually develop insulin resistance; we demonstrated that mice consuming the HFD showed impaired insulin sensitivity combined with greater insulin secretion, which is characteristic of many obese humans." (PMID 22164157, 2011). "Compared to other classical insulin resistance indexes, quantitative insulin sensitivity check index (QUICKI) was reported to have the advantage of being applicable to wider ranges of insulin sensitivity and more reproducible." (PMID 21251282, 2011). "In this respect, skeletal muscle insulin resistance is a strong determinant of T2DM, thus making improvements in insulin responsiveness a nominal feature of its treatment and prevention." (PMID 21760887, 2011). "Foxp3gfp.KI mice developed insulin resistance after 12 weeks of HFD feeding as measured by intraperitoneal glucose tolerance test (IPGTT), fasting insulin, HOMA-IR, and QUICKI." (PMID 21298111, 2011).